MMP2 (matrix metallopeptidase 2)
Diseases named in the same sentence as MMP2 in open-access papers (continued):
Sharing a sentence is not in itself a finding about the gene and the disease.
diabetes (continued). "Curcumin nanoparticles proved effective in reducing the level of MMP-2 in rats with diabetes mellitus, so they can be used as adjuvant treatment for reducing the vascular complication of diabetes mellitus." (PMID 31205590, 2019). "Quantitative gelatin zymography of ventricular extracts confirmed increased expression of MMP-2 at 12 week following induction of diabetes mellitus." (PMID 31461499, 2019). "Activated MMP2 in the mitochondria results in the accelerated apoptosis of retinal capillary cells in diabetes, which damages the retinal mitochondria by modulating Hsp60 and connexin 43 and allows cytochrome c to leak out and activate apoptotic machinery." (PMID 31892939, 2019). "The oxidative stress parameters were significantly (Mann-Whitney test p < 0.002) increased after diabetes was induced, as well as glycemia, hepatic enzymes, and matrix metalloproteinases (MMP-2 and MMP-9)." (PMID 30818888, 2019). "Mechanistically, we determined that NXT inhibited TGFβ/Smad signaling pathway and decreased CTGF expression in the kidney which resulted in restoration of diabetes-inhibited MMP2/9 expression." (PMID 29904053, 2018). "For example, matrix metalloproteinase-2 (MMP-2) activity in the IMA has been found to be associated with age, hypertension and diabetes." (PMID 29684625, 2018). "Although the concentrations for two proteins (MMP2 and sTNFR2) are slightly but significantly correlated with subject age and duration of diabetes, the differences between MA and T1D patients cannot be accounted for by any of the examined covariates." (PMID 29445381, 2018). "The only significant correlations with the duration of diabetes were found for MMP2 (T1D: r = 0.23, P < 1 × 10−5; MA: r = 0.33, P < 0.01) and sTNFR2 (T1D: r = 0.17, P < 1 × 10−3)." (PMID 29445381, 2018). "In the present study, we examined in more detail the temporal and spatial distributions of MMP-2 isoform expression in murine models of Type 1 and Type 2 diabetes mellitus." (PMID 30253743, 2018). "But C/EBPβ overexpression and the valsartan treatment ameliorated the diabetes‐induced reduction in MMP‐2 levels, and MMP‐2 was expressed at much higher levels in the C/EBPβ overexpression group than in the valsartan group." (PMID 29266779, 2018). "Genes related to cardiac remodeling of TGFβ, TNFα and MMP2 were elevated by either diabetes or AT and were reduced in CR-mice." (PMID 30071860, 2018). "The principal findings of the current study are the demonstration that two discrete MMP-2 isoforms are induced by a simulated diabetes mellitus milieu in vitro and in a widely used murine model of diabetic renal disease." (PMID 28178341, 2017). "Here we evaluated the effect of hyperglycemia and diabetes mellitus on the in vitro and in vivo expression of the two MMP-2 isoforms." (PMID 28178341, 2017). "In agreement we also found that diabetes associated increase in renal cortical TGF beta, RAGE, IL-6, IL-18, matrix metalloproteases (MMPs, MMP2 and 9) mRNA expression were prevented in treated groups." (PMID 27901066, 2016). "Proliferative retinopathy (n = 146) was associated with higher levels of MMP-2 [0.71 (0.45; 0.96)], MMP-3 [0.49 (0.28; 0.70)], MMP-10 [0.39 (0.11; 0.66)] and TIMP-1 [0.54 (0.28; 0.81)] after adjustment for age, sex, duration of diabetes and HbA1c (Model 1)." (PMID 25848912, 2015). "We examined the expression and activity of MMPs in the sciatic nerve over a 12-week timecourse of diabetes and found downregulation of both MMP-2 mRNA and levels of active MMP-2 in sciatic nerve." (PMID 25158309, 2014). "We show that levels of active MMP-2 are downregulated in peripheral nerve during diabetes and with treatment with minocycline." (PMID 25158309, 2014). "We show that MMP-2 is expressed constitutively in the sciatic nerve in vivo and treatment with minocycline or diabetes leads to downregulation of MMP-2 expression and activity." (PMID 25158309, 2014).
diabetes (continued). "The expression and activity of MMP-2 (mRNA and protein) were downregulated by either treatment with minocycline (an inhibitor of MMPs) and/or induction of diabetes." (PMID 25158309, 2014). "Decreased activity of certain MMPs (e.g. MMP-2, -3, and -9), as described in diabetes, would account for our finding of decreased urinary excretion of collagen fragments, since less collagen filaments would in this case be cleaved from the ECM." (PMID 20927192, 2010). "The levels of MMP-2 were also significantly higher in the diabetes group (median: 0.17250 ng/ml; interquartile range, 0.0735 ng/ml) compared to healthy controls (median = 0.13850 ng/ml; interquartile range, 0.0640 ng/ml; p = 0.008)." (PMID 19758433, 2009). "Strategies that interrupt the Matrix Metalloproteinase-2 (MMP-2) and Matrix Metalloproteinase-9 (MMP-9) system have been shown to reduce the ensuing threatening risk factors of vascular complications of diabetes by alteration in Extracellular Matrix (ECM)." (PMID 21593984, 2008). "Moreover, hyperglycemia-induced oxidative stress plays a critical role in activating the expression of MMPs, particularly MMP-2 and MMP-9, which have been implicated in various vascular conditions associated with diabetes." (PMID 40276785, 2025). "MMP2 is thought to be critical for cellular integrity and cell survival, and diabetes activates MMP2 in the retina and its capillary cells, which can also increase cell membrane permeability and activate apoptosis in capillary cells by regulating mitochondrial function." (PMID 38409074, 2024). "As most matrix metalloproteinases are elastase-type endopeptidases, mainly MMP2 and MMP9, the dynamic balance of MMPs/TIMPs maintains the stabilization of the ECM; however, diabetes disturbs this balance and causes atherosclerotic plaque disruption, myocardial fibrosis, and remodeling." (PMID 36865917, 2023). "Furthermore, the protective activity of MMP-2 against β-cell death ameliorated hyperglycemia and enhanced insulin secretion and islet β-cell mass in an experimental animal model of diabetes mellitus." (PMID 37047672, 2023). "In addition, spironolactone significantly attenuated the diabetes-induced increase in both urine MMP2 and MMP9 activities, confirming that MR antagonism reduced the activity of both MMPs in vivo." (PMID 36749631, 2023). "Besides obesity and diabetes, serum concentration and expression levels of MMP2 and MMP9 have also been studied in non-alcoholic fatty liver disease (NAFLD)." (PMID 37445827, 2023). "Secondly, matrix metalloproteinase (MMP) was down-regulated in vascular smooth muscle cells and monocytes in diabetes, while MMPs were important in the development of coronary aneurysms and transgenic expression of MMP-2 induced coronary artery ectasia in mice models." (PMID 35045850, 2022). "Collagen I is a potential endogenous substrate for MMPs, and the diabetes-induced changes may reflect the observed activation of tissue 72 kDa MMP-2." (PMID 33923282, 2021). "However, another study has shown that MMP2 was elevated while MMP9 was decreased in the heart of diabetes rat." (PMID 34621323, 2021). "Collagen I is a potential endogenous substrate for MMPs, and the diabetes-induced changes may reflect the observed downregulation of MMP-28 or activation of tissue 72 kDa MMP-2." (PMID 33923282, 2021). "However, the data point to potentially different roles of MMP-2 depending on conditions of diabetes." (PMID 33923282, 2021). "Thus, the observed effects of diabetes development on changes in tissue 72-kDa MMP-2 activities can also be explained through the observed effects on SOD expression and activities." (PMID 33923282, 2021). "Decreasing the MMP-2 and MMP-9 plasma levels after intraperitoneal treatment with liposomal Curcumin can constitute valuable markers for evaluating the risk of vascular complications associated with diabetes mellitus." (PMID 30818888, 2019).
diabetes (continued). "We hypothesized that two discrete MMP-2 isoforms (full length MMP-2, FL-MMP-2; N-terminal truncated MMP-2, NTT-MMP-2) are induced by high glucose stimulation in vitro and in an experimental diabetic heart model." (PMID 31461499, 2019). "Recent studies have demonstrated an association between MMP-2 and periodontitis in patients without diabetes." (PMID 31892956, 2019). "If duration of diabetes would not be taken into account, a positive association was in fact observed, which is in line with the association between MMP-2 and office PP as well as 24-h PP measurements." (PMID 29070037, 2017). "Inhibition of intracellular MMP2 may represent a new therapeutic approach for the protection of pancreatic beta cells from oxidative injury and the prevention of diabetes." (PMID 25333278, 2014). "In conclusion we suggest that MMP-2 downregulation may contribute to the regenerative deficits in diabetes." (PMID 25158309, 2014). "Rodent models of diabetes revealed the decreased expression of MMP-2 and MMP-9 in renal tissues." (PMID 23819050, 2013). "Previous findings have clarified that MMP-2 and -9 exacerbate arterial stiffening in diabetes." (PMID 23209733, 2012). "MMP-2 could be detected both in glomeruli and the tubule systems of kidneys from control and diabetes mice." (PMID 22363890, 2011). "Thus, the metalloproteinase in plasma with Mr of 72000 from both control and diabetes mice detected by gelatin zymography is MMP-2." (PMID 22363890, 2011). "It has also been shown that MMP-2 is increased in urine, suggesting that MMPs may be biomarkers for kidney changes in diabetes." (PMID 22363890, 2011). "Obtained results showed that either genetic or pharmacological strategies may contribute to the reduction of albuminuria, glomerular hypertrophy, mesangial expansion, renal inflammation, and fibrosis induced by diabetes via regulation of MMP2, MMP9, and ADAM17 activities." (PMID 33634991, 2021). "The subgroup of MMPs known as gelatinases, in particular gelatinase A (MMP-2) and gelatinase B (MMP-9), can degrade COL and denatured COL (gelatin), and their altered activity might be implicated in the pathophysiology of diabetes complications." (PMID 34069322, 2021). "Therefore, MMP-2, MMP-9, MMP-11, MMP-13, and TIMP-4 could be important biomarkers to evaluate in diabetes and associated disorders." (PMID 33419373, 2020). "Moreover, DHI inhibits CRISPR-associated gene 3, MMP2, and MMP9 expression and the formation of acellular capillaries in retinas; thus, DHI can prevent diabetes-induced apoptosis and protect retinas against diabetes-induced damage." (PMID 31892939, 2019). "Future studies on the role of the intracellular MMP-2 isoforms may result in improving our understanding diabetes-induced cardiac pathophysiologic derangement and aid the identification of new therapeutic targets in oxidative stress-induced cardiac diseases, including DM-CMP." (PMID 31461499, 2019). "Therefore, the model with adjustment for both age and diabetes duration may have been overadjusted and our results are consistent with an important role for MMP-2 in pathophysiological vascular remodeling." (PMID 29070037, 2017). "In addition, renal transplant recipients with diabetes had stiffer arteries compared to recipients without diabetes and controls, and this was significantly associated with higher MMP-2 and MMP-9 activity in the arterial wall." (PMID 29070037, 2017). "Thus we propose that strategies to activate MMP-2 may improve the regenerative capacity of peripheral nerve in diabetes." (PMID 25158309, 2014). "The study found that CRP, MMP-2, MMP-14, TIMP-2, and IFN-γ contribute to the inflammatory processes driving periodontal damage in diabetes." (PMID 40075856, 2025). "The emergence of matrix metalloproteinases (e.g., MMP2) and S100A9 in diabetes and steatosis prediction models further supports the role of adiposome-mediated remodeling and inflammatory signaling in these diseases." (PMID 40981199, 2025).
diabetes (continued). "To date, only one study has examined the effects of quercetin on proteins involved in extracellular matrix degradation, specifically matrix metalloproteinase-2 (MMP-2) and its inhibitor, tissue inhibitor of metalloproteinase-2 (TIMP-2), in a diabetes model." (PMID 39795285, 2024). "High levels of MMP-2, MMP-3, MMP-8 and MMP-9 have been found in the epithelium and stroma of melted and perforated corneas after topical NSAID use and in patients with diabetes." (PMID 38528481, 2024). "The expressions of IL17A, MMP2, IL10 and IL6 are up-regulated with diabetes that promote the progression of OP, whereas the expressions of FGF2 and VEGFA are down-regulated." (PMID 38250601, 2024). "The results indicated that the diabetes group exhibited considerably elevated expression levels of TIMP-1, MMP-2, -3, and -9 genes when contrasted with the control group (p < 0.001)." (PMID 38169923, 2023). "Specifically, in the SBECD + OTX + CHR treatment group, TIMP-1, MMP-2, MMP-3, and MMP-9 expressions dropped approximately by about 29.04, 15.12, 58.77, and 19.41 times, respectively, compared to the diabetes group." (PMID 38169923, 2023). "MMP2 gene expression was unaffected by either concentration of TNF-α, or the presence of diabetes (ND-DF n = 5, T2DM-DF n = 4) and this was mirrored at the protein level (n = 4)." (PMID 33446687, 2021). "In vivo, the ratio of MMP2/TIMP2 and MMP9/TIMP1 was also elevated in the skin of diabetes mice by qPCR analysis Therefore, MMP-2 and MMP-9 inhibitors were administered to the STZ-induced diabetic mice to evaluate the changes in skin collagen in vivo." (PMID 34777244, 2021). "MMP-2 and MMP-9 have been shown to contribute to cardiac fibrosis in diabetes and diabetes was found to be enhanced through increased oxidative stress vascular MMP-9 activity." (PMID 33923282, 2021). "MMP-2 was upregulated, MMP-9 was unchanged, and MMP-28 was downregulated in consequence of diabetes development." (PMID 33923282, 2021). "By inhibiting MMP-2 and MMP-9 with SB-3CT, collagen deposition disorder of the skin in streptozotocin-induced diabetes mice was alleviated." (PMID 34777244, 2021). "The imbalance of MMP-2/TIMP-2 and MMP-9/TIMP-1 contributes to the skin disorder of collagen deposition in diabetes patients, providing ideas for managing diabetes skin complications early." (PMID 34777244, 2021). "Increased levels of MMP-2 and MMP-9 are observed in type 1 diabetic patients and animal models, such as STZ-induced diabetes mellitus in rats, and are associated with microvascular complications of DM." (PMID 32093214, 2020). "The aim of this study was to investigate the effect of two forms of EGCG (EGCG solution and liposomal EGCG) on oxidative stress parameters, antioxidant capacity, serum MMP-2 and -9, and pancreatic and liver function in STZ-induced diabetes mellitus in rats." (PMID 32093214, 2020). "Diabetes cerebrovascular remodeling is characterized by increased vessel tortuosity, vascular endothelial growth factor (VEGF) expression, and MMP-2, and -9 activity." (PMID 29743683, 2018). "The best model for predicting liver inflammation (METAVIR grade 2–3) comprised CXCL10, TIMP1 and APRI (AUROC = 0.798); whereas the best model for predicting steatohepatitis incorporated IL8, ADIPOQ, MMP2, MMP7, age, BMI and diabetes (AUROC = 0.857)." (PMID 27861569, 2016). "NXT also inhibited the diabetes-induced expression of CAS-3 protein and mRNA, MMP-2/9 and TNFα mRNA, accumulation of carbohydrate macromolecules, and formation of acellular capillaries in the retina." (PMID 25821481, 2015). "Diabetes also significantly increased the expression of connective tissue growth factor (CTGF) and decreased expression of matrix metalloproteinase-2 (MMP-2), indicating an increase of fibrosis of the heart." (PMID 23899787, 2013). "Immunohistochemical procedures for MMP-2, MMP-9, TNF-α, IL-1β, IL-6, RANKL, and RAGE were performed in rats after 1, 3, 6, 9, and 12 months of diabetes induction." (PMID 22611374, 2012).
diabetes (continued). "These SNPs represent several distinct physiological pathways, including blood coagulation (F3), endothelial and hematopoietic stem cell proliferation (KITLG), protease pathways contributing to diabetes (CAPN10), and extracellular matrix remodeling (MMP2)." (PMID 19351393, 2009). "Increased production of Matrix Metalloproteinase-2 (MMP-2) and Matrix Metalloproteinase-9 (MMP-9) in diabetes leads to degradation of extra cellular matrix in blood vessels and enhance complications of diabetes." (PMID 21593984, 2008). "Although quercetin was reported to reduce the diabetes-induced expression of 63 kDa MMP-2, the expression and activity of 72kDa MMP-2 were not significantly affected, creating uncertainty regarding the significant effects of quercetin on modulating MMP-2." (PMID 39795285, 2024). "In patients with CKD and diabetics, serum levels of MMP-2, MMP-8, and MMP-9 were found to be higher, being correlated with serum phosphate (MMP-2), fibroblast growth factor-23 (FGF-23), and proteinuria (MMP-8 and MMP-9), which are both associated with oxidative stress and cardiovascular health." (PMID 37840653, 2023). "Additionally, the increased activities of matrix metalloproteinases 2 (MMP-2) and MMP-9 play a role in extracellular matrix degradation thereby accelerating atherogenesis and potentially reducing plaque stability in diabetes." (PMID 34055013, 2021). "The application of quercetin did not influence these diabetes-induced effects on cardiac MMP-2 activation." (PMID 33923282, 2021). "Novel drugs aiming to increase MMP-2 or decrease PTGER3 in the kidney might of great values for preventing DN and renal damages in diabetes." (PMID 33435900, 2021). "In this regard, some authors suggest that MMP-2 may be a good index of the severity of microangiopathy, and MMP-9 may be a marker of macroangiopathy in diabetes." (PMID 34069322, 2021). "On the other hand, in porcine model of STZ-induced diabetes, decreased cardiac MMP-2 activities in comparison to non-diabetic animals were demonstrated." (PMID 33923282, 2021). "The gelatinases, MMP2 and MMP9, mediate fibrosis in CKD, such as in diabetes mellitus." (PMID 34819020, 2021). "Treatment with QCT prevented the negative effects of obesity on SOD but did not modulate the diabetes-induced changes in 72 kDa MMP-2 activation." (PMID 33923282, 2021). "Based on these results, the authors postulated that MMP-2 may be a good index of the severity and stability of microangiopathy, and MMP-9 is a marker of macroangiopathy in diabetes." (PMID 32403389, 2020). "In one study, an even lower level of MMP-2 in diabetic nephropathy vs. diabetes without nephropathy was described." (PMID 31936869, 2020). "Type IV collagenases, MMP-2 (72kDa), and gelatinase-B, MMP-9 (92kDa) are most likely to contribute to the microvascular complications of diabetes mellitus, especially in diabetic retinopathy due to capillary cell apoptosis mechanism as previously reported on animal models." (PMID 30818888, 2019). "However, ergosterol treatment efficiently reversed the reduction of MMP-2 and MMP-9 in diabetic kidneys." (PMID 30823598, 2019). "In conclusion, two isoforms of MMP-2 were expressed strongly in diabetic cardiac cells and tissue and those MMP-2 isoforms may be related to the functional changes in diabetes and structural changes by extension in the more advanced diabetic models." (PMID 31461499, 2019). "We created a scoring system by using diabetes mellitus status (yes = 2, no = 0) and the median levels of MMP-2 (2 vs. 0), galectin-3 (1 vs. 0) and endothelin-1 (2 vs. 0), as cut-off points." (PMID 30413105, 2018). "Previous reports have shown that MMP-2 and MMP-9 activities were significantly upregulated in diabetic heart, and inhibition of MMP activities is considered to have a cardioprotective role in diabetes." (PMID 29760746, 2018).